CD4 (CD4 molecule)
Diseases named in the same sentence as CD4 in open-access papers (continued):
Sharing a sentence is not in itself a finding about the gene and the disease.
tumor (continued). "Therefore, we utilized a Hu-PDX mouse model to elucidate the effect of cPLA2 inhibition in modulating the tumor-infiltrating CD4+ and CD8+ lymphocytes." (PMID 35135586, 2022). "Additionally, secretion of IL-1β by lung cancer cells induces CD4+ T-cells to produce the tumor-promoting cytokine IL-22." (PMID 35086565, 2022). "The results showed that by days 6 and 10 post-treatment, only NV1042-inoculated tumors contained CD8+ and CD4+ cells, demonstrating superior anti-tumor immunity, while NV1042-treated tumors showed a significant reduction in CD31 staining, implying an effective anti-angiogenic effect of IL-12." (PMID 36293504, 2022). "The knowledge gap of CD4+ TRM cells is even bigger in the context of anti-tumor immunity." (PMID 36385379, 2022). "Analysis of tumor infiltrating immune cells showed that loss of YTHDF1 promoted the recruitment of mature dendritic cells (DCs), which contributed to increased homing of CD4+ and CD8+ T-cells to tumors." (PMID 35193930, 2022). "The correlations among the expression of six PDEMRGs and different types of immune cells in PAAD were also identified; they were correlated with the infiltration of tumor purity, CD4+ T cells, CD8+ T cells, B cells, neutrophils, and myeloid-derived suppressor cells (MDSC)." (PMID 35664305, 2022). "Importantly, knockdown of Dbp and E2f8 genes in CD4+ T cell suppresses and promotes Granzyme b, respectively, in Th9 cells in vitro and also in Granzyme B+ T cells in tumor-bearing mice in vivo." (PMID 36241625, 2022). "In the CD4-depleted mice, tumor growth of the WT cells was suppressed." (PMID 35150340, 2022). "Interestingly, the GITR expression on CD8 and CD4 TILs corroborated the anti-tumor effects of GITR treatment." (PMID 36591244, 2022). "Despite comparable capacity to induce DuoBody-CD3x5T4-dependent tumor cell kill, the frequency of activated naive T cells was lower after 24 h but higher after 48–72 h when compared with memory populations, in particular for naive CD4+ T cells." (PMID 36271507, 2022). "However, a chemical released from Bacteroides fragilis, polysaccharide A, induced the differentiation of naïve CD4+T cells to immunosuppressive pro-tumor regulatory CD4+T cells (Treg)." (PMID 35741028, 2022). "The increased frequency of cDC2 in untreated distant tumors may drive CD4+ T cells and B cells to control the distant tumor growth." (PMID 35710296, 2022). "The density of TLSs correlates with the density of CD4+ T and CD8+ T cells in the tumour and the detection of tertiary structures has been associated with a favourable prognosis for many solid malignancies, probably related to their ability to induce a durable systemic anti-tumour response." (PMID 36423077, 2022). "Our data revealed higher average fractions of some immune system cell types in the CD45+ TAS as compared to CD45+ tumor epithelium for both naïve B cells (18% vs. 15%), memory B cells (9% vs. 3%), naïve CD4 T cells (6% vs. 4%) and T follicular helper cells (Tfh) (3% vs. 1%)." (PMID 36230846, 2022). "Therefore, to achieve tumor clearance is imperative the presence of tumor specific CD4 T cells with Th1 effector function that can quantitatively and functionally overpower other potential CD4 T cells with detrimental functions such as Th2 and Tregs." (PMID 35903540, 2022). "From immune cell estimation, we observed tumor-infiltrating M2 polarization was dominated, and CD4+ T-cell tended to differentiate with Th2 cells in R/R MM tumors, both of which contributed to the suppressive immune microenvironment during MM tumor progression." (PMID 36033464, 2022). "MDSCs, especially from tumor-bearing hosts, effectively suppressed CD4+ T cell proliferation." (PMID 35089465, 2022). "Results showed that the low-risk subgroup exhibited higher mutation rate, more M1 macrophages, CD8+ and CD4+ T cells infiltrating, more active MHC-I, and bias to “IFN-γ Dominant” immune type, which is consistent with our current understanding of tumor prognostic risk." (PMID 35627105, 2022).
tumor (continued). "Studies have found that low CD4+/CD8 + ratio is related to a poor survival of tumor patients." (PMID 35280112, 2022). "These analyses point out that FAM72B may be participating in the immune response to the LUAD tumor microenvironment, particularly to B cells and CD4+ T cells." (PMID 35707363, 2022). "Considering the high proportion of Tr1 cells (considered as CD4+CD49b+Foxp3− T cells) found in the tumor site, we decided to test whether targeting CD49b could prevent tumor growth." (PMID 35860556, 2022). "A tumor immunosuppressive environment may be exacerbated by the overexpression of TIM-3 on CD4+ T cells." (PMID 36146549, 2022). "Both CD4 T and dendritic cells play significant roles in anti-tumor immunity." (PMID 36438826, 2022). "Indeed, the reduction of FOXP3+CD4+ Treg cells in tumor tissue after anti-CTLA-4 mAb (Ipilimumab) treatment was strongly associated with clinical benefit." (PMID 35601491, 2022). "We further explored the LAYN crosstalk with diverse tumor-infiltrating immune cell markers, including markers of B cells, CD4+ T cells, CD8+ T cells, tumor-associated macrophages (TAMs), monocytes, M1/M2 macrophages, neutrophils, DCs, and natural killer (NK) cells." (PMID 36398067, 2022). "To better understand the role of these CD4+ T cell subsets in tumor protection induced by EVax immunization, we examined the impact of neutralizing IFN‐γ (the major cytokine player of Th1 cells) and IL‐17a (the major cytokine player of Th17 cells) in EVax‐treated mice." (PMID 35861366, 2022). "Of note, results are divided regarding the tumor-specificity of CD4 help." (PMID 35008422, 2022). "In vivo treatment of tumor-bearing mice showed that doxorubicin, paclitaxel significantly increased the number of CD4+ and CD8+ T cells, which may be related to the expression of IFN-γ and granase B." (PMID 36304169, 2022). "Together, these results suggest that CD4-derived IL-9 promotes tumor growth and IM expansion." (PMID 35778404, 2022). "Moreover, tumor-free mice exhibited a significant increase in proportion of CD44+CD62L− effector memory T cells in CD4+ and CD8+ T cell compartments compared with that in control mice." (PMID 35764365, 2022). "The anti-tumor activity of AN3025 was abolished by CD4+ and CD8+ T cells depletion." (PMID 35251028, 2022). "The role of CD4+ T cells in anti-tumor immunity has been studied in cancer patients." (PMID 35744031, 2022). "Taken together, these findings are in line with the hypothesis that the reduction of CD4+ T cells can allow tumor advancement and reduce the survival of the host." (PMID 36005179, 2022). "Moreover, CD4+TIL-Ts exert anti-tumor effects by recognizing tumor antigens and releasing cytokines, which activate other tumoricidal immune cells." (PMID 36325319, 2022). "As a result, we speculate that LPAR5 might enhance phagocytosis and antigen presentation of macrophages, recruiting more CD8+ T cells and CD4+ activated memory T cells to infiltrate the tumor microenvironment and inhibiting tumor cell growth." (PMID 36591220, 2022). "Furthermore, tumor cells with Atg5 or Atg7 knockdown fail to elicit CD4+ and CD8+ T cell activities and deactivate the natural protective antitumor immune response." (PMID 35935871, 2022). "Moreover, the apoptosis of tumor cells enhances the availability of tumor antigens, facilitating CD4+ and CD8+ T lymphocytes to be activated by dendritic cells." (PMID 36297203, 2022). "Reducing the population of naïve T cells, which may be induced to differentiate into Tregs, may prevent the over-accumulation of conventional CD4+ Tregs in the tumor microenvironment and improve tumor immunity." (PMID 36428581, 2022). "Indeed, CD8+ TILS are more frequently found within tumor islets as evidenced by CD103 expression compared to CD4+ T cells." (PMID 35185935, 2022). "This hypothesis was corroborated by the fact that CD4 depletion prior to LAIT treatment enhances tumour killing for a period." (PMID 35808806, 2022).
tumor (continued). "Immune components account for a large part of our signature, including tumor-infiltrating lymphocytes (pro-B cells, naive B cells, memory B cells, class-switched memory B cells, and CD4+ Tcm cells), myeloid lineage cells (basophils), and stem cells (platelets and CMP)." (PMID 35795712, 2022). "Several previous studies have shown that peptides derived from tumor antigens could be presented by cancer cells to activate CD4+ T cells." (PMID 36139357, 2022). "In addition, tumor regression has been observed after ACT of TILs enriched with neoantigen-specific CD4+ T cells in cholangiocarcinoma patients." (PMID 35008422, 2022). "Tumor-infiltrating CD4+ T cells have recently been correlated with favorable prognosis in OSCCs however CD4+ T cells consist of several subpopulations (including Tregs) and CD4 expression as a prognostic biomarker in OSCCs and HNSCCs is controversial." (PMID 35957892, 2022). "We hypothesize that raised levels of circulating Hsp70 in higher tumor stages might support NK cell proliferation, but that a lowered prevalence of CD4+ T helper cells could temper the capacity of cytolytic CD8+ T cells and NK cells to control tumor growth." (PMID 36428793, 2022). "We found that not only TAMs could indeed present tumor antigens to tumor-infiltrating CD4 T cells, but that this presentation was required for tumor rejection." (PMID 35903540, 2022). "TIICs in the tumor microenvironment also influence tumor prognosis; for example, patients with thymoma with high infiltrating levels of B, CD4+ and dendritic cells (DCs) have a better prognosis and may be partially regulated by the ASF1B gene." (PMID 35928818, 2022). "This is not unexpected as CD4+ T regulatory (Tregs) cells play a significant role in tumour progression and metastases, as loss of CD4+ T cells prohibited lung metastases in untreated MMTV‐PyMT tumour bearing animals." (PMID 35808806, 2022). "(E) Levels of CD8+ and CD4+ T cells were compared in the tumor and spleen." (PMID 36458816, 2022). "Dual combination HSV/BRAFi was immunogenic as assessed by standard methods such as the CD8 to Treg ratio, but Tocky analysis revealed that only the persistent to arrested transitioning Tocky positive TCR-signaling subset of conventional CD4 +effectors correlated with reduced tumor growth." (PMID 35338089, 2022). "Another mechanism of how CD4 T cells could contribute to tumor dormancy was described by another study where they showed that the effects of CD4+ T cells were mediated through the secretion of angiogenesis inhibitors CXCL10 and CXCL9." (PMID 36430404, 2022). "In addition, the DCs directly present tumor antigens to CTLs, which are activated with the help of activated CD4+ T cells." (PMID 36355531, 2022). "The basic principles of tumor vaccine success include the delivery of large amounts of high-quality antigens to DCs, the induction of strong and sustained CD4+ T helper cells and cytotoxic T lymphocyte (CTL) responses through the activation of DCs, and the persistent infiltration of the TME." (PMID 36142800, 2022). "Despite the earlier onset of apoptosis in glycolysis-inhibited alloreactive CD8+ T cells compared to CD4+ T cells, ex vivo stimulated T cells were capable of controlling tumor development and improving survival outcome compared to TCDBM + tumor and untreated donor T cell recipients." (PMID 35296079, 2022). "B16 tumor-derived pericytes induce CD4+ T cell dysfunction or anergy." (PMID 35626052, 2022). "The T-cell subsets involved in anti-tumor immunity are mainly CD4+ and CD8+ T cells." (PMID 35694271, 2022). "Furthermore, efficient activation of both endogenous and exogenous DCs, migration of DCs to draining lymph nodes, and tumor infiltration of CD4+ and CD8+ T cells was observed." (PMID 36091031, 2022).
tumor (continued). "We found that TME scores and the relative abundance of several key tumor-infiltrating immune cells (CD4+ naive T cells, CD8+ Tcm, CD8+ Tem, Mast cells, and Tregs, NK cells, pro B cells, Th1 cells, and Th2 cells) showed significant differences between the two subtypes." (PMID 36211401, 2022). "It is assumed that the increase in CD4+CD161+ cells may be directly associated with the clinical status and tumor burden of patients." (PMID 36660546, 2022). "Moreover, this is a virally driven oncogene model, and as such a strong CD8+ T cell response likely exists well before the depletion of CD4+ T cells as these tumours were implanted first and allowed to reach a specific size before T cell depletion." (PMID 35808806, 2022). "Likewise, the enhanced expression of total and stromal CD3+ lymphocytes, and in particular the CD4+ T cell-subset, was also correlated with tumor grade III, which raises a possible defense mechanism by stromal T cells against tumor aggressiveness." (PMID 36010653, 2022). "In addition, the neoantigen nanovaccine also upregulated the Treg subgroup (CD3+CD4+Foxp3+) and the expression of PD-L1 on tumor cells." (PMID 35418151, 2022). "On the other hand, two studies described the anti-tumor activity of CD26 high-CD4+ T cells, but it is currently unclear whether, how, or at which stage DPP-IV/CD26 may play a role in the development of this T-cell subpopulation." (PMID 35565202, 2022). "Importantly, expression of PD-1 and TIM-3 on CD8+ T cells, as well as on CD4+ T cells, were positively correlated to tumor volume on day 14 and supports the concept that sustained inhibitory receptor expression is associated with lack of antitumor activity." (PMID 35507536, 2022). "However, CD4 T cells in the tumor microenvironment were unstable for a broad subpopulation with potentially different functions." (PMID 36713509, 2022). "Imatinib treatment results in tumor regression in Cd4-NPM-ALK transgenic mice." (PMID 36045346, 2022). "In addition, the fractions of immune cell subtypes related to tumor immunity, including M1 macrophages, CD4+ memory activated T cells, regulatory T cells, and CD8+ T cells, were significantly higher in the UV-high cluster." (PMID 36246650, 2022). "The CD4+ and CD8+ T cell infiltration into the stroma and tumor epithelium was further determined by CD4 and CD8 IHC staining.CD8+ T cells were further designated as CD8 TEM, CD8 TEMRA/TEFF, CD8 TRM, CD8 Naïve, CD8 IFN response, and CD8 Cycling cell subtypes, according to their marker genes." (PMID 35907904, 2022). "Furthermore, recent clinical evidence has highlighted the importance of CD4+ T cells in generating successful anti-tumor immunity." (PMID 35759090, 2022). "B7-H4 not only promotes immunosuppressive cells in TME, such as Treg, myeloid-derived suppressor cells, and macrophages, which regulate tumor-infiltrating neutrophils, but it also inhibits the activation and subsequent effector functions of CD4 and CD8 T cells in TME." (PMID 36499340, 2022). "In normoxic tumor tissues, the infiltration of CD4+ T cells, CD8+ T cells, and CD11c+ dendritic cells was more significant in the combined treatment group than the IR alone group, while the infiltration of FoxP3+ regulatory T cells showed no significant changes." (PMID 36238646, 2022). "In addition, CD4+ Tcon were closer to tumor cells than CD4+ Treg, both in the TC and IM; CD4+ Tcon and CD4+ Treg in TC were farther from tumor cells than in IM." (PMID 36685566, 2022). "CD4+ regulatory T cells (Tregs) significantly impact tumor immunity." (PMID 36444617, 2022). "Here, we report a case with EBV-SMT; the tumor shrank without surgery in close association with the CD4 count, and the phenomenon of immune reconstitution inflammatory syndrome (IRIS) was observed." (PMID 35141174, 2022).
tumor (continued). "Rather, because immune cells with killing effects were activated by YH29407, which is an IDO1 inhibitor with high pharmacokinetics and pharmacodynamics, the inhibition of CD4+ T cells, which can differentiate into Tregs, may have helped in tumor suppression." (PMID 36545214, 2022). "This could indicate some cooperation between tumor and CD4 T cells, resulting in the apoptosis of the cytotoxic population, thus preventing the elimination of the cancer cells." (PMID 36429101, 2022). "In addition, our data demonstrate that infection-induced antigen-specific effector CD4+ T cells can be used to treat tumor metastases, while antigen-specific memory CD4+ T cells can maintain protective immunity against tumor metastasis." (PMID 35784297, 2022). "Furthermore, CD4+ T cells in the tumor were composed mainly of Treg cells, indicating an important role of immune suppression by this cell type." (PMID 36700232, 2022). "This may be due to ineffective tumor-antigen presentation by dendritic cells (DC), reduced activity of CD4+ T-cells, and regulatory functions by Treg cells." (PMID 36135061, 2022). "Similarly, representative cells for anti-tumor immunity such as NK cells, memory resting CD4 T cells, Tregs, Monocytes and M0 Macrophages were more abundant in the high-APscore group (all p<0.05)." (PMID 36311733, 2022). "It is deemed that CD4+ T cells can either promote or prevent tumor progression." (PMID 35386705, 2022). "Thus, presentation of tumor antigen by bone marrow–derived myeloid cells is necessary for tumor rejection by effector CD4 T cells." (PMID 35903540, 2022). "CD4+ T cells could target tumor cells in a variety of ways, directly eliminate tumor cells through the cytolytic mechanism, or indirectly interact with tumor cells by regulating the tumor immune microenvironment." (PMID 35483337, 2022). "B cells act as antigen-presenting cells to present tumor-associated antigen (TAA) to CD4+ T cells, and then help CD4+ and CD8+ T cells to secrete interferon-γ, resulting in immediate cytotoxicity to tumor cells; meanwhile, B cells directly lyse tumor cells by secreting granzyme B and TRAIL." (PMID 35563678, 2022). "In some cancer models, CD40-mediated activation of macrophages, which possibly mimics the effects of CD4+ T cell stimulation, has been shown to drive tumor control in an IFNγ-dependent manner, resulting in substantial remodeling and collapse of the tumor’s fibrotic network." (PMID 34282297, 2022). "Its expression is linked to a better prognosis in CRC patients, as the percentage of ICOS+ CD4+ cells operating as Th1 cells in either primary tumor tissue or peripheral blood could be a clinical predictive marker for a favorable prognosis." (PMID 36072957, 2022). "BCI-induced tumor regression is not only mediated by tumor cell killing by bacteria themselves, but also by host immune cell-dependent responses by neutrophils, macrophages, and CD4+ and CD8+ T cells." (PMID 36246355, 2022). "In contrast to the domination of immature T-cells and B10 in B1 and B2 tumor subtypes, in more aggressive TETs, the immune infiltrate is composed mainly of fully differentiated CD4 and CD8 single-positive T-lymphocytes, which represent the main cellular components of anti-tumor immune reactions." (PMID 35887212, 2022). "Lower densities of CD3 and CD4 lymphocytes were seen in CRC with a greater depth of tumor invasion." (PMID 36526699, 2022). "A more appropriate indicator of suitable patients for ACT is still yet to be identified, and the CD4/CD8 ratio of the primary tumour may be a potential marker." (PMID 35158816, 2022). "In addition, activated memory CD4 T cells, Tfh cells infiltrations consistent with tumor T&M and stage trend, and M1 macrophages were correlated with distant tumor metastasis." (PMID 36186442, 2022).